TLR4 (toll like receptor 4)
Diseases named in the same sentence as TLR4 in open-access papers (continued):
Sharing a sentence is not in itself a finding about the gene and the disease.
colitis (continued). "Consistent with a role for M2a Mφ in the resolution of DSS-induced colitis, the rosiglitazone-treated TLR4-SNP mice exhibited increased expression of the M2a protein, Ym1 (Chil3), compared to the saline-treated group." (PMID 37768050, 2023). "Herein, we show that, like humans with IBD, the TLR4-SNP mice exhibit much more severe colitis in response to DSS than WT mice." (PMID 37768050, 2023). "In conclusion, TLR4-SNP mice develop more severe DSS-colitis symptoms compared to WT mice and exhibit a reduced capacity to repair colonic damage." (PMID 37768050, 2023). "Another study also showed that dietary supplementation with 1% Ile reduces the inflammatory response in mice with colitis by downregulating inflammation-related cytokine expression through the TLR4/MyD88/NF-κB pathway." (PMID 36838201, 2023). "Mice expressing homologous SNPs (“TLR4-SNP” mice) exhibited more severe colitis than WT mice in a DSS-induced colonic inflammation/repair model." (PMID 37768050, 2023). "A polysaccharide from Flammulina velutipes has been shown to alleviate colitis by controlling colonic microbial dysbiosis, increasing short-chain fatty acids, and inhibiting the TLR4-NF-κB signaling pathway." (PMID 37485384, 2023). "QA changed other genes as follows: 30 (p < .05, F.C: −3.22), 60 (p < .001, F.C: −20.8), and 100 (p < .001, F.C: −32.25) mg/kg also dexamethasone (p < .01, F.C: −4.6), significantly attenuated TLR4 expression, in comparison to the colitis values." (PMID 37647443, 2023). "Reishi has been shown to reduce AOM/DSS-induced colitis and tumourigenesis by inhibiting the TLR4/MyD88/NF-κB pathway, improving intestinal flora dysbiosis, and increasing the production of short-chain fatty acids." (PMID 37790812, 2023). "Intriguingly, TLR4 has dual effects in colitis, maintaining mucosal integrity while also intensifying colitis by promoting proinflammatory cytokine release." (PMID 37371485, 2023). "Our previous research found that experimental models of colitis activate hepatic stellate cells and TLR4 signaling through the gut-liver axis to aggravate liver fibrosis, verifying the important relationship between the gut and liver diseases." (PMID 37898694, 2023). "Previous evidence shows that G. lucidum can improve intestinal flora dysbiosis and reduce AOM/DSS-induced colitis and tumorigenesis by inhibiting TLR4/MyD88/NF-κB pathway." (PMID 37790812, 2023). "In conclusion, 3-IAld ameliorated the intestinal barrier dysfunction and inflammatory response in DSS-induced UC mice, balanced amino acid metabolism, and inhibited the activation of the TLR4/NF-kB/p38 signaling pathway, thereby protecting mice with colitis." (PMID 37175112, 2023). "Mechanically, EA treatment reduced the activation of the TRPV1/CGRP, ERK, and TLR4 signaling pathways in L6 DRG of colitis rats." (PMID 36910013, 2023). "The functional role of fuc-TLR4 signaling in mucosal repair and recovery of homeostasis was investigated by inducing colitis in BD mice." (PMID 37007789, 2023). "It has been shown to reduce the inflammatory response in colitis mice by inhibiting the Toll-like receptor 4 (TLR4)/Nuclear factor kappa B (NF-κB) pathway and NLR-family-pyrin-domain-containing 3 (NLRP3) inflammasome activation." (PMID 37444374, 2023). "Yet, the administration of melatonin was found to promote the induction of MUC2-secreting goblet cells via TLR4 stimulation in a DSS-induced model of colitis." (PMID 36768553, 2023). "In a DSS mouse model, over-expression of TLR4 has been found to enhance inflammatory responses to mucosal injury and promote colitis-induced tumorigenesis." (PMID 37761139, 2023). "Some researchers argued that curcumin activated SIRT1/NRF2 and inhibited the TLR4 signaling pathway to improve necrotizing microscopic colitis and cell pyroptosis, as well as preventing DSS-induced excessive autophagy." (PMID 37836654, 2023).
colitis (continued). "For instance, curcumin or melatonin have been shown to inhibit NLRP3 inflammasome and TLR4/MyD88/NF-κB signaling pathway respectively, reducing abdominal pain as well as acting like immune checkpoints in preclinical models of colitis." (PMID 37233492, 2023). "Curcumin reduces TNBS-induced colitis in rats by inhibiting the TLR4/NF-κB signaling pathway and pro-inflammatory IL-27 expression." (PMID 37701897, 2023). "Thymol exhibits inhibitory effects on the expression of TLR4 and the activation of NF-κB signaling in mice treated with acetic acid to induce colitis." (PMID 37701897, 2023). "After colitis is induced by lipopolysaccharide in mice, the upstream Toll-like receptor 4 (TLR4) signaling pathway activates mTOR and inhibits autophagy." (PMID 36840593, 2023). "Another LGG-secreted protein HM0539 was recently identified as an active factor effectively reducing colitis in rats via activating TLR4/MyD88/NF-кB pathway in enteric cells." (PMID 36918929, 2023). "DMB alleviated colitis and suppressed the activation of TLR4 signaling in TNBS-induced colitis rats and LPS-induced RAW264.7 cells." (PMID 37168866, 2023). "The obtained results confirmed our theory; we found a marked activation of the TLR4-MyD88 signaling pathway following DNBS-induced colitis." (PMID 37233492, 2023). "TLR4 knockout exacerbated DSS-induced colitis of TLR4−/− mice mediated by gut microbiota and the abundance of Akk was significantly decreased in TLR4−/− mice, whereas it was enriched in wild-type mice." (PMID 36835309, 2023). "A recent experimental animal study demonstrated that lycopene plays a preventive role in dextran sulphate sodium‐induced colitis mice by regulating the TLR4/TRIF/NF‐κB signalling pathway." (PMID 36645152, 2023). "Intake of EV from L. plantarum Q7 resulted in the down-regulation of inflammatory cytokines and the improvement of bacterial diversity by regulating the TLR4-MyD88-NF-κB pathway in mice suffering from induced colitis." (PMID 38138044, 2023). "For example, L. plantarum AR113 ameliorates DSS-induced colitis by regulating the TLR4-MyD88-NF-κB pathway and gut microbiota composition." (PMID 37764783, 2023). "In the colon, a TLR2/TLR4/MyD88 cascade drives mucosal repair during the regenerative phase of colitis, demonstrating the role of TLR signals in regeneration." (PMID 37936149, 2023). "Research has confirmed that EPP can alleviate colitis in rats by regulating Th17/Treg balance, suppressing the TLR4/MyD88/NF-κB signaling pathway, and modulating intestinal flora." (PMID 38231750, 2023). "Albiflorin enhanced the expression levels of Foxp3 and STAT5 in colon, decreased adrenodoxin, NF-κB, and TLR4 mRNA with the increase of Foxp3 mRNA in colitis." (PMID 36594064, 2023). "Here, we found that AA-induced colitis has led to a rise in the expression of TLR4 by qRT-PCR and NF-kB immunostaining, which is in line with previous studies." (PMID 37895902, 2023). "E. coli has been shown to promote the healing of colitis-related mucosal damage in the colon through the activation of the TLR4/NF-κB signaling pathway." (PMID 37322488, 2023). "Early studies showed that mice with natural or engineered deficiencies in TLR4 signaling (e.g., C3H/HeJ, C57BL/10ScN, TLR4−/−) exhibited increased susceptibility to chemically-induced colitis." (PMID 37768050, 2023). "Curcumin (100 mg/kg, 5 days, PO) suppressed the amount of NF-ĸB, COX-2, 5-LOX, and iNOS expression in inflammatory bowel disease, and inhibited toll-like receptor-4 (TLR-4)-induced NF-ĸB activation in experimental colitis in Sprague–Dawley male rats." (PMID 36559142, 2022). "A previous study claimed that MEL alleviated trinitrobenzene sulfonic acid-triggered colitis in rats via restraining the TLR4/NF-κB pathway." (PMID 35340691, 2022). "Our results showed that in acute colitis on day 6, TLR4 expression increased by four times in the colonic epithelial cells of AKR1B8 KO mice compared to wild type mice." (PMID 36518763, 2022).
colitis (continued). "Na2SeO3 regulates the IDO1/kynurenine, TLR4, NF- κB, and Bcl2/Bax pathways and attenuates acetic acid-induced colitis in rats." (PMID 39280958, 2022). "An anti-inflammatory effect of prostasin overexpression by downregulating TLR4 expression has been observed against colitis in the colonic epithelium." (PMID 35922613, 2022). "A research reported that oxyberberine alleviated intestinal mucosal inflammation and colonic mucosal injury in DSS-induced colitis mice by suppressing the TLR4–MyD88–NF-κB signaling pathway." (PMID 35484567, 2022). "In summary, GM, fecal metabolites, infDCs, and TLR4/NF-κB signaling have important roles in the effects of SSP against colitis mice with SKYD syndromes." (PMID 36310616, 2022). "While we clearly demonstrate increased intestinal permeability at baseline in vitro and in vivo, for the DSS colitis we relied on LPS serum measurements by TLR4 reporter cells as an indicator for a leaky barrier." (PMID 36271073, 2022). "In this study, the increased expression of TLR4 in the IECs of AKR1B8 KO mice indicates the activation of this innate signaling pathway under acute colitis induced by DSS." (PMID 36518763, 2022). "We found that both mRNA and protein expression levels of TLR4 were elevated in DSS-induced colitis mice, corresponding to the results of increased inflammation caused by DSS." (PMID 35992694, 2022). "We then investigated the expression of TLR4 in the colonic epithelial cells in acute colitis induced by DSS at 1.5% in drinking water." (PMID 36518763, 2022). "Studies have shown that TLR4 signaling is activated during IBD pathogenesis, and the activated TLR4 signaling triggers innate NF-κB signaling and promotes pro-inflammatory cytokine production, contributing to colitis." (PMID 36518763, 2022). "A mechanism responsible for the development of the inflammatory reaction in colitis is the activation of TLR4." (PMID 35204289, 2022). "Based on the results, the gene expression of inflammatory mediators counting TNF-α, IL-1β, and TLR4 noticeably amplified in the colitis group in comparison to the control group (P < 0.05)." (PMID 35432569, 2022). "In conclusion, these data indicate that HO protects against DSS-induced colitis by inhibiting TLR4/NF-κB pathway activation and improving intestinal barrier function through activation of the endogenous opioid system." (PMID 36176442, 2022). "Colitis was more severe in Akk[BMT(WT)→TLR4−/−] than in Akk[BMT(TLR4−/−)→WT] after 2.5% DSS administration, as measured by the DAI score and colon length." (PMID 35761415, 2022). "The results suggested that Jat plays a protective role in DSS-induced colitis by regulating the intestinal barrier function and inhibiting the TLR4/MyD88/NF-κB signaling pathway." (PMID 36193153, 2022). "Baicalin ameliorated TNBS-induced colitis injury by suppressing TLR4 signaling in a concentration-dependent manner, inhibiting NF-κB activation and limiting the inflammatory response, such as ICAM-1, MCP-1, Cox-2, TNF-α, IL-1β and IL-6." (PMID 35484567, 2022). "In order to observe this process in colitis mice, Western blotting was used to detect the levels of the TLR4/NF-κB signaling molecules." (PMID 36310616, 2022). "Previous findings indicated that ginsenoside (Rg1) dampened inflammatory diseases like colitis by inhibiting the binding of LPS to TLR4 on macrophages and restoring the Th17/Treg ratio." (PMID 35729638, 2022). "Findings showed that anethole at doses of 62.5 (P < 0.01), 125 (P < 0.001), and 250 mg/kg (P < 0.001) meaningfully reduced the expression of TLR4 in comparison to colitis (saline-received) mice." (PMID 35432569, 2022). "Our results show that the NAMPT, TLR4, and CYBB genes associated with mouse colitis share functions with those of humans." (PMID 36552583, 2022).
colitis (continued). "In this study, aggravated colon inflammation in TLR4−/− mice was accompanied by a significantly reduced proportion of RORγt+ Treg cells, while mitigated colitis in WT mice was accompanied by a relatively higher frequency of suppressive RORγt+ Treg cells." (PMID 35761415, 2022). "Accordingly, our results confirmed for the first time that HO ameliorates DSS-induced colitis via inhibiting TLR4/NF-κB pathway activation and regulating intestinal homeostasis." (PMID 36176442, 2022). "Administration of α-TREM-1 alleviated colitis in mice and resolved dysbiosis, which required TLR4/Myd88 signaling." (PMID 33767714, 2021). "Surprisingly, also CD45+ leukocytes, isolated from the intestinal epithelium and the lamina propia of mice suffering from DSS-induced colitis, displayed enhanced TLR4 expression." (PMID 34025672, 2021). "To determine the immune regulatory mechanism of mEVs in DSS-induced colitis model, we examined the expression of several crucial regulators in the TLR4-NF-κB and NLRP3 signaling pathways by western blotting, immunohistochemistry and RT-PCR analysis." (PMID 34373759, 2021). "Overall, DSS-induced colitis promoted the activation of HSCs and TLR4 signaling through the gut-liver axis in CCl4-induced liver fibrosis mice." (PMID 34603071, 2021). "Ultimately, Cel/PT-LbL Lipo significantly mitigated colitis symptoms and accelerated colitis repair in DSS-treated mice by regulating the levels of pro-inflammatory factors related to the TLR4/MyD88/NF-κB signaling pathway." (PMID 34959287, 2021). "In a TNBS-colitis ICR mouse model, Soyasaponin Ab treatment was shown to attenuate colitis severity and inhibit NF-κB activation and expression of TLR4." (PMID 33916612, 2021). "A previous animal study showed that IL-27 is involved in the immunopathology of TNBS-induced colitis in rats via the TLR4/NF-κB signaling pathway." (PMID 34744512, 2021). "GQL can be used to treat inflammation and oxidative stress so as to reduce the severity of colitis by inhibiting TLR4/NF-κB activation." (PMID 34381354, 2021). "In this models, PEA anti-inflammatory effects were also closely related to the specific reduction of enteric glial cells (EGCs) activation during colitis, mediated by the selective targeting of the S100B/TLR4 axis." (PMID 33986673, 2021). "After curcumin treatment, the protein levels of TLR2, TLR4, MyD88, NF-κBp65, p38MAPK, and AP-1 in the colonic tissues of colitis mice were significantly reduced." (PMID 34567209, 2021). "In the current study, we show that acute DSS colitis affects TLR4 expression on innate immune cells as well as on epithelial cells in the colon." (PMID 34025672, 2021). "The expression of both TLR4 and MyD88 was significantly down-regulated in HnAb treated colitis mice relative to vehicle-treated DSS-induced colitis mice." (PMID 33193406, 2020). "On the other hand, compared with that observed inwith the control group, the DSS-induced colitis model group had greatly increased mRNA levels of TLR4, JAK2 and STAT3." (PMID 32762699, 2020). "While TLR4 activation is essential to drive Th17 responses, its effects on Th1 cells are rather inhibitory in a spontaneous model of colitis and in human T cells exposed to LPS, where signaling via TLR4 inhibited cell migration." (PMID 32547564, 2020). "Studies with antibiotics suggest that PAMPs released by commensal organisms also activate TLR2/TLR4 in DSS colitis." (PMID 33552081, 2020). "Combined, these results indicated that obacunone exerted a protective effect against DSS-induced colitis through attenuation of TLR4/NF-κB signaling cascades." (PMID 32296403, 2020). "Compared with the control group, the DSS-induced colitis group had significantly enhanced gene and protein expression of TLR4." (PMID 32762699, 2020). "Recently, alpinetin was shown to provide protection against DSS-induced colitis in mice via blockade of toll-like receptor-4 (TLR4)/NF-kB signaling pathway and NOD-like receptor protein 3 (NLRP3) inflammasome activation." (PMID 32372959, 2020).
colitis (continued). "TAK-242 markedly alleviated DSS-induced colitis symptoms and colonic lesions by promoting IL-10 release, inhibiting IL-17 release, downregulating TLR4 and JAK2/STAT3 mRNA and protein expression and increasing JAK2/STAT3 phosphorylation." (PMID 32762699, 2020). "The goal of the present study was to investigate the effects of TAK-242 on the gut microbiota and the TLR4/JAK2/STAT3 signaling pathway in mice with dextran sulfate sodium (DSS)-induced colitis." (PMID 32762699, 2020). "Compared with the control group, mice treated with DSS showed an obvious upregulation of the protein expression of TLR4 in colitis tissue." (PMID 32762699, 2020). "Here, we reported that pinocembrin eased the severity of dextran sulfate sodium (DSS)-induced colitis in mice by suppressing the abnormal activation of toll-like receptor 4 (TLR4)/nuclear factor-kappa B (NF-κB) signal pathway in vivo." (PMID 32687156, 2020). "The first step in wound repair in DSS colitis is TLR4 activation in pericryptal macrophages resulting in the migration of COX-2 expressing MSCs from the lamina propria near the upper crypts to sites adjacent to epithelial cells in the lower crypts." (PMID 33552081, 2020). "In conclusion, we have shown that high consumption of monosaccharides and disaccharides increases pro-inflammatory tuning of the organism, compromises the gut barrier function, and worsens colitis in a TLR4-dependent manner." (PMID 33339337, 2020). "In the repair phase of DSS colitis endogenous HA drives epithelial proliferation through TLR4 activation." (PMID 33552081, 2020). "Collectively, these results suggested that TLR4/MyD88/NF-κB signaling is involved in DSS-induced development of murine colitis, and that HM0539 plays a suppressive role in the DSS-induced inflammatory response." (PMID 33123130, 2020). "The activation of Toll‐like receptor 4 (TLR4) signalling promotes inflammation in colitis of mice, but the role of TLR4 in intestinal tumorigenesis is not yet clear." (PMID 31650683, 2020). "The protective effect of this antibody was enhanced in TLR4-deficient mice in some aspects, indicating that both additional HMGB1-mediated as well as TLR4-mediated inflammatory signaling pathways were involved in the induction of colitis by DSS." (PMID 33193406, 2020). "It confirms that CRHR2 receptor antagonists (Astressin2B) can block the TLR4/NF-κB signaling pathway in DSS-induced colitis mice to reduce the levels of TNF-α, IL-6, and IL-1β in serum, thereby protecting the colon mucosa." (PMID 30881446, 2019). "The current results clearly indicate that ASB possesses potential anti-inflammation therapeutic efficacy through inhibiting the activation of TLR4 signaling against DSS-induced colitis and LPS-activated macrophages." (PMID 31207873, 2019). "Previous studies reported that the activation of TLR2 and TLR4 expression on macrophages and dendritic cells was involved in the pathogenesis of mouse colitis." (PMID 31921214, 2019). "In this experiment, a rat model of colitis was established to explore probiotic VSL#3 inhibiting the expression of TNF-α in rats with colitis through TLR4-NF-κB signal pathway." (PMID 31497551, 2019). "Further, by using TLR4 null mouse models they have demonstrated that HNE mediates inflammatory signaling in DSS-induced colitis by signaling through TLR4." (PMID 31781341, 2019). "Probiotic VSL#3 inhibits the expression of NF-κB and TNF-α in rats with colitis through TLR4-NF-κB signal pathway, so it is expected to be a first choice drug for the treatment of colitis." (PMID 31497551, 2019). "Evidence indicates that n-3 PUFAs and n-9 PUFAs, respectively, upregulate the TLR-2 and TLR-4 genes of TNBS-induced colitis, while n-6 PUFAs influence high-mobility group box 1 (HMGB1), a reactivator of TLR gene." (PMID 31780872, 2019). "They suggested that there is interference between PPARγ and TLR-4 signaling pathways in a sense that PPARγ can significantly prevent colitis by reducing NF-κB activity." (PMID 31011554, 2019).